ABHD17B (abhydrolase domain containing 17B, depalmitoylase)
Description:
Hydrolyzes fatty acids from S-acylated cysteine residues in proteins. Has depalmitoylating activity towards DLG4/PSD95. Has depalmitoylating activity towards GAP43 (By similarity). Has depalmitoylating activity towards MAP6 (By similarity). Has depalmitoylating activity towards NRAS.
Synonyms: C9orf77; FAM108B1; CGI-67
Tractability: Antibody: its Gene Ontology location is reachable by antibodies, with high confidence; UniProt places it where antibodies can reach, with medium confidence. PROTAC: ubiquitination databases record sites on it; its protein half-life has been measured.
Target class: Enzyme; Hydrolase
Chemical probes: ABD957 (high quality)
Gene: Protein-coding gene on chromosome 9 (71,862,452 to 71,911,224, reverse strand). Ensembl gene ENSG00000107362.
Subcellular location: Cell membrane; Recycling endosome membrane; Cell projection, dendritic spine; Postsynaptic density membrane
Pathways (Reactome):
Signal Transduction: RAS processing
Gene Ontology:
Molecular function: palmitoyl-(protein) hydrolase activity
Biological process: protein depalmitoylation; negative regulation of protein localization to microtubule; positive regulation of protein localization to endosome; regulation of postsynapse organization; regulation of dendritic spine maintenance; regulation of protein localization to synapse
Cellular component: membrane; endosome membrane; plasma membrane; dendritic spine; glutamatergic synapse; postsynaptic density; postsynaptic density membrane; postsynaptic recycling endosome membrane; recycling endosome membrane
Genetic constraint (gnomAD): Loss-of-function variants: 9 observed, 27.12 expected, observed/expected ratio (o/e) 0.33, 90% interval 0.2 to 0.58. The upper end of that interval is the gene's LOEUF score, 0.58, which puts it in group 2 of 6, group 1 being the genes least tolerant of losing a copy. Missense variants: 224 observed, 370.33 expected, observed/expected ratio (o/e) 0.6, 90% interval 0.54 to 0.68. Synonymous variants: 127 observed, 129.07 expected, observed/expected ratio (o/e) 0.98, 90% interval 0.85 to 1.14.
Homologues: Orthologues: dog ABHD17B (100% identical), pig ABHD17B (100% identical), guinea pig ABHD17B (99% identical), mouse Abhd17b (99% identical), rat Abhd17b (99% identical), chimpanzee ABHD17B (99% identical), macaque ABHD17B (99% identical), rabbit ABHD17B (99% identical), tropical clawed frog abhd17b (97% identical), zebrafish abhd17b (50% identical), Caenorhabditis elegans F01D5.8 (38% identical), Caenorhabditis elegans F01D5.7 (38% identical). Paralogues in human: ABHD17A (78% identical), ABHD17C (78% identical), ABHD12 (26% identical), ABHD12B (24% identical), ABHD13 (20% identical), ABHD16A (18% identical), ABHD16B (16% identical).
Diseases named in the same sentence as ABHD17B in open-access papers:
ABHD17B is named in the same sentence as 3 diseases in open-access papers, as found by Europe PMC text mining. Sharing a sentence is not in itself a finding about the gene and the disease. The quoted sentences say what the papers report.
liver fibrosis (1 paper, 2022). "Since the expression of ABHD17B was suppressed by TGF-β, we concluded that during liver fibrosis, TGF-β facilitates HK1 secretion by inhibiting ABHD17B-dependent depalmitoylation of HK1." (PMID 36192599, 2022).
ABHD17B also shares sentences with these, for which no sentence is quoted: cancer (1 paper); metabolic disease (1).